TERT (telomerase reverse transcriptase)
Diseases named in the same sentence as TERT in open-access papers (continued):
Sharing a sentence is not in itself a finding about the gene and the disease.
glioma (continued). "The LR and LRLasso models, mainly based on T1-enhanced entropy and GLSZM, showed good predictive ability for TERT promoter mutations in gliomas using radiomics models." (PMID 39131044, 2024). "For predicting the TERT promoter mutation status in glioma patients, we utilized a combination of feature selection methods, including ANOVA, Relief, and RFE, along with classification algorithms such as LR, LRLasso, SVM, AE, LDA, and NB." (PMID 39131044, 2024). "Although IDH-mutated glioma cells lack TERT mutations, they are able to reactivate the telomerase TERT and stabilize their telomeres in association with increased expression of c-MYC target genes, including TERT." (PMID 37626776, 2023). "Canonical glioma genetic alterations occurred in most tumors as initiating truncal events, including TERT promoter mutations, chromosome 7 duplication and chromosome 10 monosomy." (PMID 37770427, 2023). "Radiomic features from conventional T1 with contrast (T1c) and FLAIR MRI sequences have been exploited to predict the mutation status of IDH or TERT promoter in gliomas." (PMID 36176070, 2023). "Telomerase reverse transcriptase (TERT) promoter mutations are also under scrutiny for their role in telomere maintenance in gliomas." (PMID 38139688, 2023). "Previous studies have suggested that TERT mutations are associated with a poor prognosis in tumours, such as thyroid malignancies, melanoma and gliomas." (PMID 37897649, 2023). "Total tumor resection, preoperative KPS score ≥60, IDH1/2 gene mutation, postoperative radiotherapy and chemotherapy were associated with better survival of patients with gliomas, while TERT promoter mutation was associated with poor survival (P<0.05)." (PMID 37250582, 2023). "have underscored the significance of isolated TERT promoter mutation in glioma and its correlation with improved prognosis, amidst the plethora of molecules under investigation." (PMID 37483487, 2023). "Highlighting that IDH1/2 gene and TERT promoter mutation are related to the prognosis of patients with glioma." (PMID 37250582, 2023). "All three immune subtypes harbored grade 2, 3, and 4 gliomas, IDH mutant gliomas, 1p19q codeleted gliomas, and TERT promoter mutated gliomas." (PMID 36688633, 2023). "Already incorporated into WHO classification of glioma, Telomerase Reverse Transcriptase (TERT) promoter mutations extend telomeres to produce immortal cancer cells." (PMID 37860270, 2023). "Stepwise multivariate Cox hazard regression showed that the grade, age, TERT mutation, and our subtypes were tended to be the independent risk factors for glioma survival, with the cluster based on lncRNA methylation being the most significant factor." (PMID 37056564, 2023). "TERT promoter mutations are a very frequent event in central nervous system tumors (CNS), especially in gliomas." (PMID 38201248, 2023). "Our results showed that the combined chromosome 7 gain/10 loss and TERT promoter mutation associated with high INTS9 in the IDH wildtype astrocytoma during the CDKN2A/CDKN2B homozygous deletion in the IDH mutant glioma." (PMID 37537630, 2023). "TERT-promoter mutations (TERT-pmt) are known to be amongst the most common and the earliest mutations in the most invasive gliomas." (PMID 36831683, 2023). "Recently, there has been increasing interest in utilizing radiomics based on multi-parameter MRI for the prediction of TERT mutations in gliomas." (PMID 37830090, 2023). "A significant association of TERT mutations in gliomas with a higher proportion of tumor-infiltrating neutrophils has also been confirmed." (PMID 38275375, 2023).
glioma (continued). "On the other hand, the polymorphism rs2853669 has been largely detected in lower-grade gliomas and is associated with a decreased TERT expression since it leads to the disruption of the ETS2 binding sequence." (PMID 38201248, 2023). "Glioblastomas are the most common IDH-wildtype adult high-grade gliomas, frequently harboring mutations in the TERT gene promoter (pTERT) and utilizing the subsequent telomerase overexpression for telomere length maintenance." (PMID 37891325, 2023). "Terzi et al19 showed that mutations in TERT promoter region accounted for about 50~60% of gliomas, and their histopathological types and proportions were different." (PMID 37250582, 2023). "Patients with IDH-mutated gliomas show better prognosis, while patients with TERT-mutated glioma show compromised overall survival and progression-free survival." (PMID 38111070, 2023). "TERT codes for telomerase reverse transcriptase, a protein key to the maintenance of telomeres and one whose expression is upregulated in a subset of gliomas through promoter mutation or by other means to facilitate tumor progression." (PMID 37454191, 2023). "In particular, the two most common somatic mutations in TERT promoter, C228T and C250T, which are present in almost 60% of glioma patients were investigated in both CTCs and parental tumors." (PMID 37373295, 2023). "The mutations of IDH1/2 and TERT promoter were analyzed, and risk factors affecting survival of the patients with glioma were assessed." (PMID 37250582, 2023). "Several radiomics models have been developed in previous research to predict TERT promoter mutation status in patients with gliomas." (PMID 38054695, 2023). "Two BRAF-rearranged gliomas had TERT promoter mutations and five had loss of CDKN2A/B, all of which were grade 4." (PMID 36854806, 2023). "Although multi-parametric radiomics has demonstrated promising results in accurately and sensitively predicting TERT mutations in gliomas, previous studies have primarily focused on grades 2–4 gliomas with limited investigation into GBM." (PMID 37830090, 2023). "p-TERT pathogenic variants are reported in 51% of all glioma types and together with IDH-WT constitute the most common genotype in glioblastoma." (PMID 37908227, 2023). "Radiomics performed on magnetic resonance imaging (MRI) were shown to predict molecular alterations such as IDH1/2 mutations, 1p19q co-deletion, ATRX status, MGMT promoter methylation and also TERT promoter mutations in gliomas with remarkable accuracy." (PMID 37686690, 2023). "Correspondingly, the detection of a TERT promotor mutation now qualifies the diagnosis of anaplasia according to the current fifth edition of the WHO Classification of Central Nervous System Tumours, with potential subsequent impact on postoperative treatment." (PMID 37686690, 2023). "The prognostic power of the TERT promoter mutation highlights its potential use as an important biomarker to predict the aggressive clinical behavior in melanoma, glioma, medulloblastoma, bladder cancer, thyroid cancer, urogenital cancer, and laryngeal cancer." (PMID 35135543, 2022). "We analysed DNA extracted from FFPE glioma tissue samples of 73 patients for TERT promoter hotspot mutations at hg19 chr5 nucleotides 1,295,228 (“C228T”) and 1,295,250 (“C250T”) using commercially available ddPCR assays." (PMID 35361262, 2022). "Although TERT mutation prevalence is over 80% in gliomas, their role as a prognostic/predictive biomarker is still largely controversial." (PMID 35888045, 2022). "The most common non-FGFR1 alterations were IDH1/2 mutations (234 cases), KIAA1549-BRAF fusion (73 cases), 24 TERT C228/C250-mutated gliomas and 35 cases with NF1." (PMID 35018490, 2022). "NGS analysis detected TERT promoter mutations in 33 out of 45 investigated gliomas (72.7%), 12 of which harbored the hot-spot C250T (c.1-146C>T) mutation and 21 carrying the C228T (c.1-124C>T) variant." (PMID 35372034, 2022).
glioma (continued). "More recently, co-deletion of 1q/19q and mutation in TERT is also important in prognosis and treatment option of glioma." (PMID 35931979, 2022). "The combination of IDH genotype, 1p/19q co-deletion, or TERT promoter mutation status is often used to evaluate the prognosis of patients with gliomas." (PMID 35807084, 2022). "A couple studies utilizing AI/radiomics have shown that high grade gliomas with TERT promoter mutation are associated with higher volumes of necrosis." (PMID 35436952, 2022). "Although less prevalent overall in gliomas compared to the mutually exclusive TERT promoter mutations, ATRX mutations and ALT are frequent in specific molecular subgroups of sporadic brain tumors, particularly IDH mutant astrocytomas." (PMID 35740680, 2022). "TERT promoter mutations were independently associated with poorer overall survival in all glioma subtypes." (PMID 35931979, 2022). "In gliomas, TERT expression and TERT promoter mutation are considered to reliably indicate telomerase activation, while ATRX mutation and/or loss indicates an alternative lengthening of telomeres (ALT)." (PMID 35953846, 2022). "in the same issue of New England Journal of Medicine, in addition to using IDH and 1p19q, introduced also TERT mutation to stratify low-grade gliomas." (PMID 35558510, 2022). "TERT promoter mutations have been found in central nervous system tumors, including primary glioma (up to 80%), medulloblastoma (20%), and meningioma (6.4–11%)." (PMID 35931979, 2022). "In previous studies, the revertant mutation of TERT -124 in glioma cells induced cellular senescence; however, we found that senescence-associated biomarker β-galactosidase activity was inconspicuous in A375−146T/C and A375−146C/C cells." (PMID 35053139, 2022). "The regulation of telomerase expression in gliomas has been shown to depend on the mutational status of the TERT promoter (TERTp)." (PMID 35327529, 2022). "ATRX (ATP-dependent helicase) and TERT (telomerase reverse transcriptase) mutations are usually present together and are essential for further differentiation of gliomas." (PMID 34687436, 2022). "In melanoma, glioma, hepatocellular carcinoma, urothelial carcinoma, and others, TERT promoter mutations have been found to define subsets of patients with adverse disease outcomes." (PMID 35559034, 2022). "TERT promoter mutation is associated with worse prognosis in melanoma, glioma, meningioma, thyroid cancer, and bladder cancer and is also associated with a high risk of malignant transformation and progression to advanced stages in hepatocellular carcinoma." (PMID 35135543, 2022). "Given that 67.9% of tumours being TERTp-mut, TERT is the most frequently mutated gene in gliomas thus far identified." (PMID 34558656, 2022). "On the contrary, a TERT-only mutated glioma is more deeply located than IDH-MUT and 1p/19q codeleted tumors." (PMID 36289752, 2022). "Researchers have established radiomics-based classification models to predict TERT promoter mutation status in patients with gliomas, and some progress has been made." (PMID 35807084, 2022). "Overall, TERT promoter mutations were present in 57 of 84 (67.9%) gliomas [20 (60.6%) in grade II, 12 (66.6%) in grade III, and 25 (92.5%) in grade IV]." (PMID 34558656, 2022). "The values of nADC and omADC were higher in TERT promoter wildtype (TERT-wt) gliomas than in TERT-mutated gliomas (P = 0.046 for nADC and 0.041 for omADC)." (PMID 36471242, 2022). "For instance, FGFR3-TACC3 fusion and TERT promoter mutation are more closely associated with adult-type glioma, H3 K27-altered mutation is associated with pediatric-type glioma and EGFR mutation to both." (PMID 35436952, 2022). "TERT promoter mutations are correlated to increased TERT expression and a worse prognosis as confirmed by a recent meta-analysis in glioma patients." (PMID 36313663, 2022).
glioma (continued). "In this review, we consider the methodological approaches used to determine mutations in the promoter region of the TERT gene in tumors of the central nervous system." (PMID 35327529, 2022). "We constructed MR-based radiomic models for predicting the status of IDH mutation, 1p/19q codeletion, and TERT promoter mutation prior to surgery in gliomas." (PMID 34312469, 2021). "Mutant IDH1 1p/19q-codel gliomas are usually oligodendrogliomas and frequently co-express mutations in TERT promoter (TERTp) and CIC." (PMID 34168976, 2021). "Consensus clustering analysis was used to sort glioma samples into two clusters according to the expression profile of four survival-associated AGs (TERT, LEP, PON1, and SSTR3)." (PMID 34114970, 2021). "A subgroup of adult-type diffuse mutant IDH1 gliomas which harbor 1p/19q chromosomal co-deletions (1p/19q-codel) and TERT promoter mutation are now classified as oligodendrogliomas." (PMID 34422657, 2021). "We did not observe significant difference of SCG3 expression between gliomas grouped by other common genetic features in gliomas, such as TERT promoter mutations and MGMT promoter methylation." (PMID 34257545, 2021). "In glioma harboring telomerase reverse transcriptase (TERT) promoter mutations, TERT and EZH2 cooperate with fatty acid synthase (FASN) and induce fatty acid accumulation." (PMID 34737746, 2021). "In case of TERT promoter mutation, TERT mutated gliomas (n = 42) showed higher PD-L1 expression compared with TERT wild-type gliomas (n = 5, p > 0.05)." (PMID 33963441, 2021). "This study was, to our knowledge, the first to analysis perfusion parameters evaluated by combining IDH mutation status and MGMT methylation status and TERT mutation status in glioma gene detection results." (PMID 34814870, 2021). "In terms of TERT, we found higher PD-L1 expression in TERT mutated glioma (mean amounts of 32%) compared with TERT wild-type glioma (mean amounts of 20%, p > 0.05)." (PMID 33963441, 2021). "The only GWAS of glioma in an East Asian population confirmed associations near TERT, PHLDB1 and RTEL1, and identified two new variants [32•]." (PMID 34817716, 2021). "Mutation of the telomerase reverse transcriptase (TERT) promoter has been demonstrated as an unfavorable prognostic marker in patients with isocitrate dehydrogenase wild-type (IDHwt) glioma." (PMID 33996815, 2021). "Abnormal upregulation and activity of TERT as a consequence of TERTp-mutations are considered one of the mechanisms of cellular immortality in cancer cells during division, particularly in gliomas." (PMID 33996563, 2021). "For example, glioma with IDH or TERT mutation has a better prognosis, and glioma with H3F3A or HIST1H3B/C mutation is classified as diffuse midline glioma and has a poorer prognosis." (PMID 34393714, 2021). "To further stratify the immune variation of TERT mutated tumors in glioma microenvironment, we analyzed the enrichment scores of 26 immune cell-characterized gene sets across TERT mutation status." (PMID 33996815, 2021). "To better understand the mechanism of TERT mutation in IDHwt glioma, we determined the differentially expressed genes between TERT wild-type and mutation." (PMID 33996815, 2021). "Among the molecular features that define low-grade gliomas, mutually exclusive mutations in the TERT promoter and ATRX, which define LGOGs and LGAs, respectively, are notable because they both lead to TMMs." (PMID 33397920, 2021). "In our study, we successfully established a Sanger sequencing-based molecular screening method for detecting TERT promoter mutations in glioma samples." (PMID 34159191, 2021). "Three studies were included that described the classification of the TERT promoter mutation status in glioma." (PMID 34073309, 2021).
glioma (continued). "In contrast, most IDH-O and a large fraction of IDH-wt gliomas maintained telomere lengths via activation of telomerase (TEL) after promoter mutations of the TERT gene, which kept telomere lengths short but slightly above the telomere crisis threshold." (PMID 34206856, 2021). "Enhanced expression of TERT in gliomas is a result of two hotspot mutations, C228T and C250T, at the promoter region." (PMID 34194624, 2021). "Various studies have reported that telomerase activation or increased TERT expression are associated with shorter survival in gliomas." (PMID 34638714, 2021). "Reactivation of telomerase reverse transcriptase via pTERT alterations plays a pivotal role in gliomas with pTERT mutations found in 80–90%, correlating with higher TERT mRNA and protein expression, and subsequent increased telomerase activity." (PMID 33547950, 2021). "Although still under investigation, it has been suggested that TERT promoter mutations characterize gliomas that require aggressive treatment." (PMID 34073309, 2021). "This study was, to our knowledge, the first to analysis perfusion parameters were evaluated by combining IDH mutation status and TERT mutation status in glioma gene detection results." (PMID 34814870, 2021). "Very few studies have applied non-invasive MRI-based models to predict TERT promoter mutation is lower-grade or high-grade gliomas." (PMID 34312469, 2021). "In glioma, TERT promoter mutations was considered as potential biomarker and mitochondrial localization of hTERT induced by oxidative stress is known to trigger apoptosis." (PMID 34199460, 2021). "Grade II/III gliomas with TERT promoter mutations alone harbored worse prognosis as compared with tumors with all three alteration." (PMID 33613747, 2021). "Two TERT promoter hotspots are recurrently mutated (C228T and C250T) across a large fraction of cancers of the central nervous system (43%), bladder cancer (59%), melanoma (29%), and other cancer types." (PMID 33832990, 2021). "We confirmed that majority of the TERT promoter mutations coincided with 1p/19q codeletion in IDH-mutated gliomas." (PMID 33228806, 2020). "TERT promoter mutation can significantly promote TERT expression, and TERT can reactivate the telomerase function, which is required as an impetus in gliomas originated from low-rate self-renewal tissue." (PMID 33195221, 2020). "In MGMT-methylated (MGMT-meth) gliomas, the presence of the TERT promoter mutation was associated with an improved OS (HR = 0.73; 95% CI = 0.55–0.98; p-value = 0.04)." (PMID 32957941, 2020). "For example, given the spectrum of aggressive phenotypes, tumor marker-based classification, such as IDH mutation, 1p/19q co-deletion, and TERT promoter mutations, predict favorable prognosis in gliomas." (PMID 33228738, 2020). "Our previous study, along with others, indicated that the prognostic value of TERT promoter mutation in gliomas is influenced by the status of IDH mutations." (PMID 32957941, 2020). "In the grade II-III glioma group, there was a significant difference in survival between the TERT-mutated-1p/19q codeleted group and TERT-wildtype-1p/19q intact group (p < 0.0001)." (PMID 33228806, 2020). "In gliomas, the prognostic impact of TERT promoter mutation has been known to be modulated by IDH mutations." (PMID 32957941, 2020). "While TERT promoter mutation showed a poor survival prognosis in glioma patients, O6-methylguanine-DNA methyltransferase (MGMT) methylation has long been recognized as an important factor in treatment decisions, and is also a positive prognostic factor." (PMID 32957941, 2020). "Strikingly, TERT mutation was common and found to be frequent in many malignancies, such as sex cord‐stromal tumor, bladder cancer, and glioma." (PMID 32810393, 2020).